MTOR (mechanistic target of rapamycin kinase)
Diseases named in the same sentence as MTOR in open-access papers (continued):
Sharing a sentence is not in itself a finding about the gene and the disease.
Sepsis (continued). "The foundation for this hypothesis is due to mTOR being demonstrated to be an essential component of the inflammatory response as well as underlying the glycolytic switch observed during acute sepsis." (PMID 33616039, 2021). "Previous evidence has indicated that the protein kinase B/mammalian target of rapamycin (AKT/mTOR) signaling pathway is implicated in the improvement of brain dysfunction by exogenous recombinant human erythropoietin through reducing neuronal apoptosis in sepsis." (PMID 31830649, 2020). "Therefore, due to the complexity of mTOR signaling, rapamycin may cause unwanted toxicity, which is likely the reason of inconsistent test results of rapamycin in preclinical sepsis models." (PMID 30744190, 2019). "Furthermore, the relationship between autophagy and the mTOR pathway in cardiac dysfunction caused by sepsis is still unknown, which was investigated in this study." (PMID 30050390, 2018). "Here, we characterise genetic variation that modulates MTOR, a critical regulator of metabolism and immune responses in sepsis." (PMID 41741465, 2026). "In the context of sepsis, the inhibition of mTOR has been shown to facilitate the clearance of damaged organelles, mitigating cellular stress, and enhancing survival." (PMID 41041277, 2025). "Targeting the PI3K/Akt/mTOR pathway emerges as a promising therapeutic approach to modulate the immune response and improve organ protection in sepsis." (PMID 41041277, 2025). "The article systematically reviews the synergistic effects of key pathways, such as HIF-1, mTOR, and sirtuins, in the immunometabolic reprogramming of sepsis." (PMID 41244772, 2025). "ZFAS1, activated by SP1, aggravates the progression of sepsis-induced cardiac dysfunction via targeting miR-590-3p/AMPK/mTOR signaling-mediated autophagy and pyroptosis of cardiomyocytes." (PMID 40041174, 2025). "Studies in a lethal candidal sepsis model revealed that the mammalian target of rapamycin (mTOR) signaling pathway is hyperactivated in CD8+ T cells, leading to impaired autophagy flux and subsequently exacerbating apoptosis." (PMID 41462924, 2025). "For instance, in murine models of sepsis, hyperactivation of the mTOR signaling pathway has been shown to induce pyroptosis in CD4+T cells, exacerbating immunosuppression associated with sepsis." (PMID 41041277, 2025). "In sepsis, activation of the mTOR signaling pathway by inflammatory mediators and growth factors promotes protein synthesis and cell proliferation." (PMID 41244772, 2025). "Intriguingly, our pre-clinical work identified the mTOR-Akt signaling pathway as a critical regulator of ERS in sepsis." (PMID 40933998, 2025). "Key signaling pathways—including HIF-1α, mTOR, in various stages of sepsis, relevant pathways play core and interrelated roles." (PMID 41244772, 2025). "Beyond this, accumulating evidence highlights the AMPK/mTOR axis as a central regulator of autophagy in sepsis." (PMID 41186245, 2025). "It was recently found that the mTOR pathway played vital role in regulation of CD4+ T-cell apoptosis through autophagic lysosomal fusion dysfunction during sepsis." (PMID 39104530, 2024). "Resveratrol can protect the myocardium during sepsis by activating the PI3K/Akt/mTOR pathway and inhibiting the NF-κB signaling pathway and related inflammatory factors." (PMID 38716051, 2024). "MiR-15b-5p and miR-378a-3p have been documented to be upregulated in platelet exosomes during sepsis, activating the Akt/mTOR-related autophagy pathway in neutrophils, resulting in overproduction of NET and exacerbating the severity of sepsis." (PMID 39104595, 2024). "Conversely, high-dose VC obviously decreased phosphorylated PI3K, AKT (except 1 days) and mTOR in CLP-induced sepsis rat cardiomyocytes at three points in time (p < 0.05), but it did not affect the phosphorylation of PI3K and AKT at 1 day." (PMID 38643461, 2024).
Sepsis (continued). "Having demonstrated the significant protective effect of endothelial MTOR in models of direct lung injury (i.e., LPS inhalation and aspiration), we assessed the capability of EC-MTOR expression in the lung to attenuate mortality from a systemic sepsis model." (PMID 39510184, 2024). "Meanwhile, blocking the PI3K/AKT/mTOR signaling pathway during sepsis triggers autophagy and blocks apoptosis." (PMID 38643461, 2024). "Delivering MTOR cDNA specifically to the lung EC as a therapeutic measure improved survival from sepsis." (PMID 39510184, 2024). "Because cMaf can protect against septic shock, this information highlights the mTOR pathway as a potential therapeutic target for sepsis." (PMID 38716051, 2024). "Mechanistically, we identified that, in sepsis, the Akt/mTOR/SREBP2 signaling pathway is augmented in naive CD4+ T cells, promoting cholesterol metabolism and facilitating Treg differentiation and functionality." (PMID 38888975, 2024). "Activation of SIRT3 attenuates the sepsis-induced AKI by modulating the AMPK/mTOR signaling to enhance autophagy." (PMID 38345033, 2024). "The first one was that activation of PI3K/AKT/mTOR signaling pathway can improve sepsis-induced cardiac dysfunction." (PMID 38643461, 2024). "Inhibition of PI3K/AKT/mTOR signaling pathway can enhance autophagy and thus reduce oxidative stress and apoptosis in LPS -induced sepsis." (PMID 38643461, 2024). "In our study, Dex treatment reversed the increased expression of p-mTOR and reduced Beclin-1 levels induced by sepsis." (PMID 38419889, 2024). "Sivelestat sodium has an interventional effect on ALI in sepsis by inhibiting the PI3K/AKT/mTOR signalling pathway." (PMID 38935660, 2024). "The loss of AQP4 polarity is considered to lead to Ca2+ overload and inhibits PPAR-γ/mTOR-dependent autophagy in astrocytes, which subsequently activates astrocytes and impairs BBB-glymphatic function in sepsis-associated encephalopathy." (PMID 38976012, 2024). "Ketamine facilitates autophagy in alveolar type II epithelial cells after LPS treatment and in a sepsis-induced acute lung injury mouse model by regulating AMPK/mTOR pathway activation." (PMID 39220589, 2024). "As the ultimate measure of its efficacy, we tested the therapeutic potential of MTOR expression in the lung endothelium against sepsis-induced mortality." (PMID 39510184, 2024). "These EVs exacerbate the inflammatory response in sepsis by promoting pro-inflammatory activation of monocytes via inhibition of the mechanistic target of rapamycin (mTOR)." (PMID 39744123, 2024). "The effect of the mTOR/HIF−1α pathway on the ultrastructural changes in the intestinal mucosal epithelial model induced by sepsis needs to be further explored." (PMID 38654163, 2024). "The PI3K/AKT/mTOR pathway is related to immunosuppression in septic mice, providing a new target for the treatment of sepsis." (PMID 38582846, 2024). "Excessive or unresolved inflammation promotes this imbalance: Inflammation inhibits the mammalian target of rapamycin (mTOR) signalling pathway that promotes MPS, and this contributes to the net muscle protein loss observed during critical illness and sepsis." (PMID 38302945, 2024). "mTOR activation is completely inhibited in CD4+ lymphocytes of patients with sepsis; however, AMPKα activation was only slightly affected, and in the case of mTOR blockade, stimulated T cells were unresponsive." (PMID 37434129, 2023). "According to a recent systemic pharmacological analysis, XBJ can affect sepsis by acting on alterations in a number of genes involved in the PI3K/AKT/mTOR signaling pathway." (PMID 37219401, 2023). "The regulation of autophagy is a novel direction for the treatment of sepsis, in which the mTOR signaling pathway, a typical upstream node repressing autophagy, is a crucial player." (PMID 37171398, 2023).
Sepsis (continued). "Research shows that miR-15b-5p expression predicts COVID-19 severity and it is involved in mammalian target of rapamycin (mTOR) signaling pathway in sepsis-induced acute kidney injury." (PMID 37587410, 2023). "In adult mice, the mTOR pathway was found to be critical for survival of Escherichia coli-mediated sepsis." (PMID 37762476, 2023). "In the present study, we injected parenteral ω-3 PUFA solutions along with AMPK inhibitor Compound C and mTOR agonist MHY1485 into CLP-induced rats with sepsis." (PMID 36694426, 2023). "Meanwhile, the PI3K/AKT/mTOR signaling pathway was blocked during sepsis, to trigger autophagy and block apoptosis." (PMID 37219401, 2023). "We will discuss potential implications in immune-related disorders and infectious diseases by mTOR through necroptosis regulation, such as autoimmune disease, sepsis and related complications, graft rejection, and infection." (PMID 38164133, 2023). "Supporting this, a study indicated that IFNγ enhances glycolysis via the PI3K/Akt/mTOR pathway, which potentially counters spleen immunosuppression during sepsis." (PMID 38259439, 2023). "The participation of the AMPK/mTOR pathway in regulating sepsis-induced multi-organ injury after parenteral ω-3 PUFA treatment was confirmed by the western blot and qRT-PCR analyses." (PMID 36694426, 2023). "ω-3 PUFAs ameliorated sepsis development by activating the AMPK/mTOR pathway, serving as a potent therapeutic agent for sepsis." (PMID 36694426, 2023). "Our results also demonstrated that IFNγ treats sepsis by promoting the Warburg effect through the PI3K/AKT/mTOR pathway by reducing the damage, immunosuppression, and metabolic paralysis brought about by sepsis." (PMID 37434129, 2023). "Two patients died from infection on day 19 (pneumonia after chemotherapy) and day 131 (sepsis after chemotherapy) after conversion A single patient stopped mTOR-inhibitor due to recurrent infections." (PMID 37200246, 2023). "Here, we demonstrated the critical role of miR-130b-3p in attenuating sepsis-induced cardiac dysfunction via the regulation of the AMPK/mTOR signaling pathways and directly targeting ACSL4 to suppress the ferroptosis in septic cardiomyopathy." (PMID 37705752, 2023). "mTOR, a key inhibitory regulator of autophagy, plays a critical biological function in sepsis-induced AKI." (PMID 37958538, 2023). "We will further investigate XBJ’s impact on the PI3K/AKT/mTOR pathway after identifying its cardioprotective role of regulating apoptosis and autophagy during sepsis." (PMID 37219401, 2023). "When we compared mTOR levels at 24 and 120 h after the induction of sepsis, we observed a decrease in mTOR levels in the CLP group (p < 0.001) and increases in the treated septic groups (CLP + FC and CLP + NC) at 120 h (p < 0.05, both)." (PMID 36365096, 2022). "In this study, we demonstrated, for the first time, the effects of curcumin on components of the mTOR pathway (total mTOR, mTORC1, Raptor, mTORC2, and Rictor) in the heart of an experimental model of sepsis." (PMID 36365096, 2022). "mTOR expression was higher in the severe sepsis than in the mild sepsis group, suggesting higher levels of lymphocyte mobilization and metabolism in patients with severe sepsis, which seemed to be confirmed by higher levels of IL and TNF-α." (PMID 35898496, 2022). "Multivariate regression analysis indicated that the increased level of mTOR and PD1, as well as reduced level of IFN-γ in CD4+ T cells were independent risk factors for 28-day mortality in patients with sepsis." (PMID 35898496, 2022). "We investigated how components of the mTOR pathway are affected by the induction of experimental sepsis and the administration of curcumin." (PMID 36365096, 2022). "We used T cell specific-mTOR/tuberous sclerosis complex 1 (TSC1)-knockout mice to explore the roles of the mTOR pathway in modulating autophagy during sepsis." (PMID 35435531, 2022).
Sepsis (continued). "In mice, sepsis promotes collagen synthesis in lung fibroblasts through the activation of the PI3K-Akt-mTOR/PFKFB3 pathway, eventually leading to pulmonary fibrosis." (PMID 35453505, 2022). "In experimental sepsis, pharmacological inhibition of mTOR was shown to be cardioprotective, which can be explained by the acceleration of autophagy." (PMID 36365096, 2022). "H2S stimulates autophagy by blocking Mammalian target of rapamycin (mTOR) signaling in sepsis-induced acute lung injury." (PMID 36233122, 2022). "In sepsis, when peripheral blood neutrophils are pathologically activated by LPS, H3K4me3-marked histone was overexpressed and mTOR dominated within H3K4me3-marked histone." (PMID 35757755, 2022). "By working to alleviate ROS-mediated, ERS-induced CD4+ T cell apoptosis, the mTOR pathway is vital for CD4+ T cell survival in sepsis mouse model." (PMID 35915740, 2022). "Our data suggest that vitamin C alleviates LPS-induced myocardial injury by inhibiting pyroptosis via the ROS-AKT/mTOR signalling pathway and thus provide novel insights into the prevention of sepsis-induced myocardial dysfunction." (PMID 36550401, 2022). "In summary, we identified AE as a potent anti-inflammatory and antioxidant compound that was able to protect against LPS-induced inflammation in our murine sepsis model at least in part via suppressing PI3K/Akt/mTOR signaling." (PMID 35978995, 2022). "Taken together, these results suggest that the mTOR pathway plays a critical role in regulation of CD4 + T-cell apoptosis during sepsis, partly through regulation of A-L fusion-related protein transcription." (PMID 35435531, 2022). "Ferroptosis in sepsis-induced acute lung damage has been shown that it can be attenuated by blocking mTOR signaling and autophagy." (PMID 35726235, 2022). "Resveratrol protected the myocardium in sepsis by activating the PI3K/AKT/mTOR pathway and inhibiting the NF-κB signaling pathway." (PMID 35464384, 2022). "Currently, research on rapamycin in sepsis has been limited to the activation of autophagy and inhibition of pyroptosis through inhibition of mTOR, thereby reducing septic response, septic brain injury, and cognitive impairment in septic mice." (PMID 35990689, 2022). "Corroborating these findings, a study employing mice with the endothelial-restricted knockout of MTOR, Raptor (MTORC1), or Rictor (MTORC2) found that the knockout of MTOR complexes augmented lung injury caused by sepsis." (PMID 36291185, 2022). "Itraconate inhibits macrophage ferroptosis via the Nrf2 pathway; hydrogen sulfide attenuates ferroptosis and blocks mTOR signaling in sepsis-induced acute lung injury." (PMID 35990689, 2022). "The PI3K/AKT/mTOR signaling is critical not only in sepsis induced by bacterial infection but also in the host response to several viral pathogens, including coronavirus infection." (PMID 35453505, 2022). "Here, we investigated the effects of curcumin on the mTOR pathway in the hearts of mice with experimental sepsis induced by ligation and perforation of the cecum (CLP)." (PMID 36365096, 2022). "Transcriptomics showed significant changes in glycolysis and the mTOR/HIF-1α signaling pathway during sepsis." (PMID 35090526, 2022). "In a CLP model of sepsis, rapamycin, an mTOR inhibitor, activated autophagy and alleviated sepsis-induced myocardial dysfunction." (PMID 36188562, 2022). "Salidroside inhibits the inflammatory response induced by LPS by inhibiting ROS-mediated PI3K/Akt/mTOR pathways, thus improving sepsis-induced cardiotoxicity." (PMID 35482440, 2022). "The mammalian target of rapamycin (mTOR) pathway modulates CD4 + T cell survival during sepsis through mechanisms that are not fully understood." (PMID 35435531, 2022). "In our study, we found that Bax, caspase-3, and BIM expression levels decreased, whereas Bcl-2 expression increased, and the CD4+ T cell apoptosis rate decreased significantly in the lck-mTOR sepsis mice." (PMID 35915740, 2022).
Sepsis (continued). "Another study also proved that inhibiting the mTOR pathway can protect the heart from sepsis in a CLP rat model by increasing autophagy." (PMID 33869205, 2021). "The metabolic signature observed here during the prolonged phase of sepsis is characterized by decreased mitochondrial and glycolytic derived energy, consistent with a state of impaired mTOR activity." (PMID 33616039, 2021). "The authors described that the inhibition of mammalian target of rapamycin (mTOR)-pathway in the early stage of sepsis with metformin decreased the production of proinflammatory cytokines (TNF, IL-1B, IFN-γ) in monocytes exposed to β-glucan." (PMID 34575294, 2021). "By modulating PTEN/AKT/mTOR signaling pathway and inhibiting the autophagy, TG reduced the sepsis induced myocardial tissue damage." (PMID 33260422, 2020). "In the present study, the metabolism signaling of PDK1 and mTOR probably determines the innate immunity in sepsis." (PMID 32774145, 2020). "In a rat model of sepsis, RSV was reported to inhibit related inflammatory factors and the NF-κB signaling pathway and activate the PI3K/mTOR signaling pathway, thereby protecting the myocardium during sepsis." (PMID 32878067, 2020). "Some studies have confirmed that during the severe stages of sepsis, beneficial autophagic activities are inhibited by mTOR activation." (PMID 32158395, 2020). "Identified molecular targets of miR‐193a‐5p included IL‐10, which is known to correlate with the CURB‐65 score and is associated with increased mortality in patients with CAP37 and mTOR, which has been shown to be down‐regulated in sepsis due to CAP." (PMID 32916773, 2020). "To assess the activation of mTOR, a key signaling pathway that regulates T-bet expression, in Candida sepsis, we used western blotting to detect the levels of p-mTOR and p70S6 kinase." (PMID 32431684, 2020). "To further investigate if the mTOR pathway regulated T-bet expression in Candida sepsis, we used T-cell-specific mTOR knockout (Lck-mTOR) mice and T-cell-specific TSC1 knockout (Lck-TSC1) mice." (PMID 32431684, 2020). "During lethal Candida sepsis, mice in which the mTOR signaling pathway was inhibited by T-cell-specific mTOR deletion had higher expression of T-bet and CD4+ T cell count than WT mice had." (PMID 32431684, 2020). "mTOR activity significantly increased after infection and further increased with aggravation of sepsis, which indicates that mTOR is involved in regulating CD4+ T cells in Candida sepsis." (PMID 32431684, 2020). "The mTOR pathway was activated after infection and its activity increased with progression of sepsis." (PMID 32431684, 2020). "A recent study has shown that blocking the mTOR pathway had a protective effect on CLP-induced sepsis cardiac dysfunction, and this effect was mediated by the acceleration of autophagy." (PMID 31507440, 2019). "Pathway analysis identified upregulation of the complement system in synovial joint sepsis and the downregulation of eukaryotic translation initiation factors and mTOR signalling pathways in both OA and OC compared to the healthy group." (PMID 31028944, 2019). "Sirtuin3 (SIRT3) overexpression promoted autophagy in CLP mice, it up-regulates p-AMPK and down-regulates p-mTOR, attenuates sepsis-induced AKI, renal tubular cell apoptosis, and accumulation of inflammatory cytokines in the kidney." (PMID 31507440, 2019). "In line, mTOR-independent induction of autophagy was also reported in a distinct population of PMN from sepsis patients which showed increased PMA-triggered NET formation activity." (PMID 31191523, 2019). "In particular, IFN-γ as well as IL-10-activated CBMΦ completely fail to increase glycolysis and furthermore show reduced activation of the mTOR pathway, which is important for survival in sepsis." (PMID 30976008, 2019).